HMGA2 (high mobility group AT-hook 2)
Diseases named in the same sentence as HMGA2 in open-access papers (continued):
Sharing a sentence is not in itself a finding about the gene and the disease.
tumor (continued). "By increasing the proportion of adjacent stromal cells within the co-culture system, we observed a notable increase in the population of SPC+ tumor cells, accompanied by a corresponding decrease in Hmga2+ tumor cells." (PMID 39930268, 2025). "The COL4A and HMGA2 enrichment analysis indicated that both of them were mainly expressed in tumor cells and immune cells." (PMID 40351420, 2025). "HMGA2 was detected in at least one case in 118 of 144 tumor categories, with strong staining in 92 categories." (PMID 40518465, 2025). "Further, HMGA2 silencing resulted in apoptosis of tumor cells and impaired the migration and invasion abilities." (PMID 38361751, 2024). "The upregulation of LIN28 accelerates the progression of various cancers via reciprocal regulation of the tumor suppressor miRNA, let-7, which suppresses oncogenes such as HMGA2, MYCN, and KRAS." (PMID 39420119, 2024). "Overall, HMGA2 overexpression in patients with BC and BC cells appears to be closely related to tumor progression." (PMID 38753081, 2024). "This sequestration results in the elevation of let‐7a's target, HMGA2, a significant orchestrator of tumor metastasis." (PMID 38522008, 2024). "HMGA2 experiences dysregulation within diverse malignant tumor tissues and is duly recognized as an oncogene intricately linked to the malignancy and prognostication of neoplastic conditions." (PMID 39591457, 2024). "Recent research showed that exosomal HMGA2 from the Epstein–Barr virus promoted tumor metastasis and EMT." (PMID 38361784, 2024). "In a variety of tumour types where HMGA2 is overexpressed, members of the let-7 miRNA family can inhibit the expression of HMGA2." (PMID 38836981, 2024). "HMGA2, an oncogene widely reexpressed in various cancers, regulates tumor cell functions through diverse mechanisms." (PMID 38493165, 2024). "In-depth studies on the crucial mechanisms of HMGA2 in tumor development and progression are of great significance for the development of HMGA2-targeted therapies." (PMID 39591457, 2024). "Deletion of HMGA2 inhibits tumor malignancy through cell proliferation, metastasis, and xenograft tumor growth in vivo." (PMID 38493165, 2024). "HMGA2 enhances tumor cell invasiveness, metastasis, and chemoresistance by affecting cellular biological processes, leading to the failure of many cancer treatments." (PMID 39591457, 2024). "Further, overexpression of the lncRNANEAT1, contributes to malignant tumor proliferation, and lncRNANEAT1 can contribute to cell metastasis by negatively regulating the miR-211/HMGA2 axis." (PMID 38753081, 2024). "The ability of HMGA2 to regulate cancer stemness highlights its importance in tumor development and progression." (PMID 39085703, 2024). "Immunohistochemistry staining of HMGA2 in 30 TNBC tumor samples demonstrated that it can contribute to lymph node metastasis." (PMID 38753081, 2024). "Compared with those in normal tissues, significantly greater HMGA2 transcription (p = 4e-8) and protein expression (p = 6e-5) were detected in tumor tissues." (PMID 38493165, 2024). "High tumour staining for each of HMGA2, MUC5AC/6, IDH1, PIWIL2, DNA index, and RPL34 was significantly associated with poorer OS upon multivariable analysis." (PMID 38398089, 2024). "Recent investigations in oncology have illuminated the significant involvement of the HMGA2 in key processes of tumor formation, such as the epithelial–mesenchymal transition (EMT) and the development of new blood vessels (angiogenesis)." (PMID 38473181, 2024). "The tumor is positive for high mobility group A2 (HMGA2), estrogen receptors (ERs), a cluster of differentiation 34 (CD34), and desmin immunomarkers." (PMID 39803071, 2024).
tumor (continued). "Several promising molecular markers with prognostic significance were also identified, including tumour HMGA2, MUC5AC/6, IDH1, PIWIL2, and DNA index." (PMID 38398089, 2024). "Accumulating evidence indicates that HMGA2 primarily acts as a downstream factor of long non-coding RNAs (lncRNAs) for regulating tumor progression." (PMID 38361784, 2024). "Silencing circTHSD4 suppressed the proliferation and the tumor formation of PCa cells through targeting miR-203/HMGA2 axis." (PMID 38361751, 2024). "For example, let-7 was discovered to serve as a tumor suppressor via targeting the expression of HMGA2 in colon cancer." (PMID 38671227, 2024). "Strell et al27 investigated the relationship between age, sex, stage, and tumor differentiation with HMGA2 protein expression and its effect on survival in cases of PDAC (n = 253) and AAC (n = 155)." (PMID 37787719, 2023). "But it also brings us new thinking, and the development of new targeted drugs against HMGA2 expression is expected to be used to delay tumor progression, which provides clinicians with a new therapeutic direction." (PMID 38304037, 2023). "On the other side, decreased expression of tumor suppressor miRNAs, such as miR-218 and let-7, promote tumor invasiveness in GC by eliminating repression of the Robo1 pathway and increasing high mobility group AT-hook 2 (HGMB2) expression, respectively." (PMID 37371856, 2023). "The presence of HMGA2-positive expression was correlated with an importantly shorter OS in the patient groups with AAC (P < .001) as well as in the neoplasia group (P = .012)." (PMID 37787719, 2023). "Through the comparative analysis of tumor tissue and normal tissue, it was found that there was a significant correlation between the expression level of HMGA2 and different tumor types." (PMID 38304037, 2023). "Multi-omic analysis showed that KP tumor organoid cells exhibit two major cellular states: one more closely resembling AT2 cells (SPC-high) and another with loss of AT2 identity (hereafter, Hmga2-high)." (PMID 36993454, 2023). "Through proteomics and bioinformatics analyses, we found that HMGA2 was overexpressed in PRCC tumor tissues, and exhibited a shorter survival rate in patients who had high HMGA2 levels." (PMID 37283291, 2023). "MiR-498-5p is a known tumour suppressor in NSCLC that targets high mobility group AT-hook 2 (HMGA2)." (PMID 37667197, 2023). "According to the literature, HMGA2 can promote angiogenesis in tumor tissues, which not only provides nutrients to tumor tissues but also facilitates the extensive metastasis of tumor cells." (PMID 38304037, 2023). "More and more studies have shown that HMGA2 plays an important role in the development and progression of tumors by regulating tumor cell metastasis, epithelial-mesenchymal transition (EMT), and stemness of cancer stem cells." (PMID 38304037, 2023). "The BER-supporting function of HMGA2 enhances the ability of tumor cells to promote the timely repair of base lesions, thus reducing replication fork stalling and promoting genome maintenance under DNA stress." (PMID 36980621, 2023). "HMGA2, which is known to promote tumor growth through various mechanisms, is found to be highly expressed in the majority of human malignancies, including HNSCC/OSCC." (PMID 37237385, 2023). "It was revealed that SMYD3 was positively correlated with HMGA2 expression in most tumor and normal tissues and cell lines." (PMID 37237385, 2023). "HMGA2 mediates multiple mechanisms of tumor progression including stimulation of proliferation and inhibition of apoptosis." (PMID 37297004, 2023). "The HMGA2 expression was observed to increase the risk of disease-related death and decrease overall survival (OS) in AAC and the neoplasia group (P = .002 and P = .016, respectively)." (PMID 37787719, 2023).
tumor (continued). "HMGA2 expression also predicts recurrence-free survival, proliferation, tumor size, nuclear grade, and metastasis in TNBC patients." (PMID 36814601, 2023). "By measuring the expression level of HMGA2, the prognosis of patients with different tumor types can be judged more accurately." (PMID 38304037, 2023). "More and more studies have shown that HMGA2 plays a very important role in the formation and development of drug resistance in tumor cells." (PMID 38304037, 2023). "HMGA2 maintains the capacity for stem cell renewal in embryonic and cancer tissues and is a known promoter of epithelial-to-mesenchymal transition in tumor cells." (PMID 36980621, 2023). "Through proteomics and bioinformatics analyses of PRCC, we found that high‐mobility group protein A2 (HMGA2) was highly expressed in tumor tissues, and patients with high HMGA2 expression exhibited shorter survival times." (PMID 37283291, 2023). "For example, in the case of BC, there is a positive association between the lncRNA HOTAIR and metastasis; HOTAIR acts as a miR-20a-5p sponge, significantly impacting the migration and invasion of tumor cells by modulating the HOTAIR/miR-20a-5p/HMGA2 pathway." (PMID 37348024, 2023). "Studies have shown that HMGA2 can act as a regulator of cell proliferation, and its expression is increased in many types of human tumor tissues." (PMID 38304037, 2023). "Using differential gene analysis between the cell states, we found that CD44 can be used to distinguish SPC-high cells from Hmga2-high cells in 7 days KPY tumor organoids." (PMID 36993454, 2023). "In meta-GEO dataset, HMGA2 was overexpressed in tumor samples compared with the normal samples, and patients with elevated HMGA2 expression had a worse prognosis than those with low HMGA2 expression." (PMID 37237385, 2023). "They observed that the presence of lymph node metastases, poor tumor differentiation, and advanced tumor stage were correlated with HMGA2 protein expression, and increased HMGA2 protein expression was an independent poor prognostic factor." (PMID 37787719, 2023). "The mounting investigation has revealed that HMGA2 levels are increased during tumor malignancy, and HIF-1α and VEGF are among the downstream genes that are induced by HMGA2, and trigger tumor cell migration." (PMID 37924077, 2023). "HMGA2 is an oncofetal protein involved in cell proliferation, neoplastic transformation, and tumor invasion." (PMID 37760460, 2023). "At the same time, HMGA2 can promote drug resistance in tumor cells, which will provide a new theoretical basis and strategy for clinical anti-tumor drug therapy, but more experiments are still needed to verify this." (PMID 38304037, 2023). "The levels of circSHKBP1 and HMGA2 in tumor tissues were decreased, while miR-766-5p expression was increased after treatment with sh-circSHKBP1 (P <0.05)." (PMID 35502885, 2022). "Previous in vitro studies from our and other groups using ACHN cell lines have shown that HMGA2-knockdown significantly depressed the cell proliferation, metastasis behavior and tumor growth." (PMID 35439951, 2022). "We further discovered that the expression of HMGA2 was inversely correlated to the percentage of tumor necrosis post neoadjuvant chemotherapy." (PMID 35388973, 2022). "Collectively, these results suggest that tumor cells expressing and consequently secreting higher levels of HMGA2 acquire greater metastatic potential through weakened endothelial barriers in vivo." (PMID 35388172, 2022). "Responses occurred independently of PD-L1 expression, and tumor RNAseq data identified HMGA2 as a potential biomarker of response." (PMID 36568239, 2022). "In a study aiming to understand the role of HMGA2 in regulating tumour development and progression, cDNA microarray was applied to investigate the mRNA expression profile of ovarian surface epithelial cells with various levels of HMGA2." (PMID 35501821, 2022).
tumor (continued). "Results revealed that oe-circ_0000658 + sh-NC-treated mice exhibited increased tumor volume and weight, while further inhibition of HMGA2 reversed this effect relative to oe-circ_0000658 alone." (PMID 35031054, 2022). "The expression of Lin28 targeted SOX2, and HMGA2 oncogenes were also suppressed by these inhibitors, supporting that these compounds can block the pluripotency of tumor cells and suppress treatment-resistant tumor progression." (PMID 36428779, 2022). "Our findings show that HMGA2-silencing was sufficient to suppress the cell transformation and xenograft tumor growth in vivo, which is consistent with our hypothesis that HMGA2-induced renal carcinogenesis occurs at least in part through regulating tumor associated EMT gene expression." (PMID 35439951, 2022). "Tumor lumps derived from subcutaneous tumors derived from 5-8F control or 5-8F HMGA2 OE cells were transferred into the livers of nude mice." (PMID 35388172, 2022). "Nearly two-thirds of patients display genetic alterations where the HMGA2 gene and 12q13-15 chromosomal aberrations are shown to be involved in the pathogenesis of the tumour." (PMID 34648617, 2022). "In humans, HMGA2 is classified as an “oncofetal” gene that promotes tumor progression and metastasis when overexpressed in cells." (PMID 34878116, 2022). "circ_0007331 knockdown reduced the activity and proliferation of tumor cells as well as migration and invasion through the circ_0007331/miR-205-5p/HMGA2 axis." (PMID 35400282, 2022). "Altogether, our study uncovered the tumor-promoting role of circ_0000658 in BCa via the miR-498/HMGA2 axis." (PMID 35031054, 2022). "Previous experimental studies suggested the role of miR-let-7b in suppressing tumors, which works by inhibiting tumor proliferation, invasion, and adhesion via interacting with various genes named HMGA2, RDX, DIAPH2, Ras c-myc, and PKA133." (PMID 35831411, 2022). "We also revealed that the inhibition of HMGA2 reversed the trends of circ_0000658 overexpression on tumor volume and EMT markers in vivo." (PMID 35031054, 2022). "HMGA2 overexpression has also been strongly associated with advanced TNM stage, tumor local invasion and distal metastasis, tumor differentiation and unfavorable prognosis." (PMID 35439951, 2022). "In this manuscript, we report that expression of HMGA2 in tumor samples from patients who experienced disease control was 32-fold higher than expression of HMGA2 in samples from patients who had PD." (PMID 36568239, 2022). "The tumor tissues examined the impacts of circTRIM28 knockdown and tamoxifen treatment on circTRIM28, miR-409-3p, HMGA2, PCNA, Cleaved-caspase 3, and MMP9 expression." (PMID 36180890, 2022). "Members of the let-7 family are known tumor suppressors that modulate oncogenes such as HMGA2, MYC and RAS." (PMID 36613487, 2022). "The results showed that sgRNA-mediated knockout of Hmga2 significantly impaired tumor growth in both C57BL/6 and BALB/c subcutaneous tumor models." (PMID 34976223, 2022). "An example of replacement therapy is the restoration of miR-34a expression in various types of cancer (e.g., lung, colon, pancreas), which led to inhibition of tumor development and inducing programmed cell death by regulating Notch 1, HMGA2 or Bcl-2." (PMID 35269947, 2022). "The inhibition of circ_0007331 increased tumor cell viability, clone formation, migration, and invasion through the miR-205-5p/HMGA2 axis." (PMID 35400282, 2022). "This efficient CRISPR/Cas9-3NLS/sgHMGA2 delivery and HMGA2 gene editing ability has also been verified in mice, which can significantly inhibit tumor growth in mice." (PMID 36119467, 2022). "The inhibition of circ_0007331 decreased the tumor cell viability, clone formation, migration, and invasion through the miR-205-5p/HMGA2 axis." (PMID 35400282, 2022).
tumor (continued). "By immunohistochemistry, DAM is typically a desmin-positive myofibroblastic tumour with variable expression of HMGA2, α-smooth-muscle actin (from 27% to 95% of cases) and CD34 (from 17% to 50%)." (PMID 35204448, 2022). "Recent studies pointed out that HMGA2 not only influenced tumor progression but also acted as an indicator to evaluate the efficacy of chemotherapeutic medications." (PMID 35502885, 2022). "Overall, our findings identify a role for HMGA2 in NPC distant metastasis via altering tumor microenvironment, suggesting that it is a promising prognostic biomarker and therapeutic target for metastasis." (PMID 35388172, 2022). "Whole-transcriptome exploratory analysis of RNAseq data from tumor samples identified high expression of the high mobility group AT-hook 2 (HMGA2) gene as a potential predictive biomarker of response to bintrafusp alfa in TNBC." (PMID 36568239, 2022). "As tumor suppressors, let-7 miRNAs inhibit oncogenes expression including c-Myc, K-ras, HMGA2 and cell cycle factors." (PMID 33446221, 2021). "BMI-1-1 and HMGA2 promote self-renewal in stem cells via negative regulation of the expression of the tumor suppressors Ink4a and Arf." (PMID 33668453, 2021). "In endometrial cancer, the overexpressed lncRNA miR-210-HG sponges miR-337-3p/137, increasing HMGA2 expression and modulating the malignancy of the tumor via TGF-β/Wnt pathway." (PMID 34439740, 2021). "Compared with the sh-METTL3 + oe-NC group, the number of tumor nodules in sh-METTL3 + oe-HMGA2 group was significantly increased." (PMID 34419065, 2021). "CRISPR-mediated knockout of LIN28B gene, chemical inhibition of LIN28B binding to let-7, or knockdown of HMGA2 significantly diminish the metastatic potential of circulating tumor cells." (PMID 34591242, 2021). "The proposed mechanism for HMGA2 expression observed in tumor having local invasion is epithelial mesenchymal transition (EMT)." (PMID 33639654, 2021). "Our qRT-PCR results showed that circFAM73A increased the mRNA levels of HMGA2 and CD44 in xenograft tumor samples, an effect that was reversed by HMGA2 depletion." (PMID 33731207, 2021). "The disruption of the HOTAIR/miR-20a-5p/HMGA2 axis alleviates tumor growth and shrinks tumor volume in vivo." (PMID 34073224, 2021). "It was shown that metformin decreases angiogenesis and tumor growth by reducing HMGA2 levels in cervical cancer cells through regulation of miR-142-3p." (PMID 33668453, 2021). "There is considerable evidence that HMGA2 can inhibit apoptosis in tumor cells and promote tumor growth." (PMID 33668453, 2021). "In human tumor tissue, HMGA2 was also frequently found in the cytoplasm and the nucleus of tumor cells, however, nuclear staining was generally stronger." (PMID 34302528, 2021). "Recent studies reported the involvement of HMGA2 in the chemoresistant phenotype of human tumor cells through different and not completely understood mechanisms." (PMID 33648535, 2021). "Correlation of HMGA2 expression with clinico-pathological parameters revealed a significant correlation of HMGA2 nuclei staining intensity with tumor grading." (PMID 34302528, 2021). "In line with other studies, here we report a significant correlation of nuclei HMGA2 staining with tumor grading." (PMID 34302528, 2021). "HMGA2 is a tumor-progressing factor in a number of tumor contexts through modulating the critical processes of cancer." (PMID 34206586, 2021). "HMGA2 is a member of the HMGB family, is expressed in a variety of cancers, and is associated with immunopositivity and tumour aggressiveness." (PMID 33865381, 2021). "To further investigate the role of HMGA2 in TNBC, we generated TNBC cell line models with stable knockdown of HMGA2 to enable investigation of the role of HMGA2 over extended periods in tumor formation and metastasis using mice xenograft models." (PMID 34680349, 2021).